RPL22 (ribosomal protein L22)
Description:
Component of the large ribosomal subunit. The ribosome is a large ribonucleoprotein complex responsible for the synthesis of proteins in the cell.
Synonyms: EAP; L22; eL22; HBP15; HBP15/L22
Tractability: Small molecule: an approved drug acts on it; a structure with a bound ligand is known; a high-quality ligand is known. PROTAC: ubiquitination databases record sites on it; its protein half-life has been measured; a small molecule that binds it is known. Other modalities: a drug acting on it is in phase 2 or 3 trials.
Target class: Other cytosolic protein
Gene: Protein-coding gene on chromosome 1 (6,185,020 to 6,209,389, reverse strand). Ensembl gene ENSG00000116251.
Subcellular location: Cytoplasm
Subcellular location (Human Protein Atlas): Nucleoli; Nucleoplasm
Pathways (Reactome):
Metabolism of proteins: Eukaryotic Translation Termination; Formation of a pool of free 40S subunits; GTP hydrolysis and joining of the 60S ribosomal subunit; L13a-mediated translational silencing of Ceruloplasmin expression; PELO:HBS1L and ABCE1 dissociate a ribosome on a non-stop mRNA; Peptide chain elongation; Ribosome Quality Control (RQC) complex extracts and degrades nascent peptide; SRP-dependent cotranslational protein targeting to membrane; ZNF598 and the Ribosome-associated Quality Trigger (RQT) complex dissociate a ribosome stalled on a no-go mRNA
Metabolism of RNA: Major pathway of rRNA processing in the nucleolus and cytosol; Nonsense Mediated Decay (NMD) enhanced by the Exon Junction Complex (EJC); Nonsense Mediated Decay (NMD) independent of the Exon Junction Complex (EJC)
Cellular responses to stimuli: Response of EIF2AK4 (GCN2) to amino acid deficiency
Developmental Biology: Regulation of expression of SLITs and ROBOs
Disease: Viral mRNA Translation
Metabolism: Selenocysteine synthesis
Gene Ontology:
Molecular function: identical protein binding; protein binding; RNA binding; structural constituent of ribosome; heparin binding
Biological process: cytoplasmic translation; translation; translation at presynapse
Cellular component: cytoplasm; cytosolic large ribosomal subunit; cytosolic ribosome; extracellular exosome; focal adhesion; nucleus; ribonucleoprotein complex; cytosol; glutamatergic synapse; presynapse; ribosome; synapse
Genetic constraint (gnomAD): Loss-of-function variants: 2 observed, 9.77 expected, observed/expected ratio (o/e) 0.2, 90% interval 0.083 to 0.64. That is too few expected variants to judge how well the gene tolerates losing a copy. Missense variants: 65 observed, 115.31 expected, observed/expected ratio (o/e) 0.56, 90% interval 0.46 to 0.69. Synonymous variants: 32 observed, 40.32 expected, observed/expected ratio (o/e) 0.79, 90% interval 0.6 to 1.07.
Homologues: Orthologues: chimpanzee RPL22 (100% identical), dog RPL22 (99% identical), macaque RPL22 (99% identical), mouse Rpl22 (99% identical), pig RPL22 (99% identical), rat Rpl22-ps2 (99% identical), zebrafish rpl22 (95% identical), rabbit RPL22 (95% identical), tropical clawed frog rpl22 (92% identical). Paralogues in human: RPL22L1 (70% identical).
Diseases named in the same sentence as RPL22 in open-access papers:
RPL22 is named in the same sentence as 69 diseases in open-access papers, as found by Europe PMC text mining. Sharing a sentence is not in itself a finding about the gene and the disease. The quoted sentences say what the papers report.
colorectal cancer (14 papers, 2012 to 2025). A primary or metastatic malignant neoplasm that affects the colon or rectum. "For example, a loss of eL22/Rpl22 accelerates the expression of eL22L/Rpl22L1, which is a driver of cell proliferation and anchorage-independent growth in colorectal cancer." (PMID 39456968, 2024). "Previous studies showed that RPL22/eL22 is highly mutated in endometrial and colorectal carcinomas." (PMID 29207594, 2017). "These include relapsed and de novo T-cell acute lymphoblastic leukemia (T-ALL; RPL5, RPL22, and RPL10, respectively); gastric, endometrial and colorectal cancer (RPL22); multiple myeloma, melanoma, glioblastoma and breast cancer (RPL5) and others." (PMID 35052397, 2021). "The ARID1A, BCR, CHD5, RPL22 and TSC2 genes were shared mutation targets in ovarian and colorectal carcinomas." (PMID 29296220, 2017). "The high mutation rate of RPL22/eL22 was also confirmed in other studies on T-acute lymphoblastic leukemia (T-ALL), endometrial and colorectal carcinomas." (PMID 29207594, 2017). "Mutations in RPL10 and RPL22 have also been implicated in tumorigenesis and identified in additional cancer types, including the rare somatic RPL10 mutations in MM and RPL22 mutations producing truncated proteins in endometrial, gastric and colorectal cancer samples." (PMID 40805230, 2025). "Although RPL22L1 expression is induced in a compensatory manner in Rpl22−/− mice and can support translation, RPL22L1 plays a pivotal role in the malignancy of colorectal cancer, hepatocellular carcinoma, and prostate cancer." (PMID 40617352, 2025). "Specifically, CASP8, KMT2D, RPL22 and TGFBR2 alterations tended to co-occur with GIE in patients with colorectal cancer." (PMID 37165135, 2023). "In addition, mutations in the ribosomal protein genes have been found to be involved in cancers such as endometrial cancer (RPL22), chronic lymphoblastic leukemia (RPS15), colorectal cancer (RPS20), and glioma (RPL5)." (PMID 34827869, 2021). "Also, the frequency of mutations seen here is comparable to the previously reported frequency in MSI-positive colorectal cancer and emphasizes the importance of ACVR2A and TGF-β signaling in MSI-positive GC, while unraveling the oncogenic roles of RPL22 and LMAN1 requires further investigation." (PMID 23237666, 2012).
T-cell acute lymphoblastic leukemia (10 papers, 2018 to 2025). Acute lymphoblastic leukemia of T-cell origin. "Frequent RPL22 mutations were discovered in T-cell acute lymphoblastic leukemia (T-ALL), gastric cancer, and endometrial cancer as reported at the end of 2012." (PMID 40427096, 2025). "In about 10% of T-cell acute lymphoblastic leukemia cases, patients have a frameshift mutation in RPL22, which is thought to contribute to cancer progression." (PMID 35159381, 2022). "For example, 10% of primary human samples of T-cell acute lymphoblastic leukemia have loss-of-function mutations in RPL22." (PMID 32432546, 2020).
acute lymphoblastic leukemia (8 papers, 2017 to 2025). Leukemia with an acute onset, characterized by the presence of lymphoblasts in the bone marrow and the peripheral blood. "Previously we identified RPL22 as tumor suppressor that was deleted or mutated in 10% of T-acute lymphoblastic leukemias." (PMID 31581233, 2019). "Among the 23 RPs showing a decreased ratio in cancer, heterozygous deletion of RPL22 is observed in approximately 10% of T-acute lymphoblastic leukemia (T-ALL) cases." (PMID 39086661, 2024).
gastric cancer (8 papers, 2012 to 2025). A primary or metastatic malignant neoplasm involving the stomach. "Although the mechanism of Drp1 regulating tumorigenesis has been gradually deepened, few reports unmask the association between Drp1 and RPL22 in gastric cancer." (PMID 35230214, 2022). "The Drp1 inactivation-mediated anti-proliferative and pro-apoptosis effects on gastric cancer were possibly associated with nuclear import of RPL22." (PMID 35230214, 2022). "The inactivation of Drp1 facilitated cell apoptosis and inhibited the proliferation and tumor growth of gastric cancer cells, which was possibly associated with the nuclear import of RPL22." (PMID 35230214, 2022). "A study of microsatellite instability-positive gastric cancers also identified RPL22 as a recurrently mutated gene with single base deletions." (PMID 30521023, 2018). "By exploring human cancer databases available in cBioPortal, we found that in addition to in endometrial and colorectal tumors (∼5%-12%), RPL22/eL22 is also highly mutated in stomach cancer (∼8%-13%) and a pool of cancer cell lines (Cancer Cell Line Encyclopedia, CCLE, Novartis/Broad, ∼7%)." (PMID 29207594, 2017). "Thus, the implication of Drp1 in the ribosome pathway may be associated with RPL22 in gastric cancer cells." (PMID 35230214, 2022). "Mechanistically, Drp1 mediated the nuclear export of RPL22 in gastric cancer cells, leading to the development of gastric cancer." (PMID 35230214, 2022). "Of note, Drp1 inactivation notably reduced the expression of cytoplasmic RPL22 and increased its nuclear level in gastric cancer cells." (PMID 35230214, 2022). "Many studies have proved the important regulatory role of RPL22 in various types of cancer including gastric cancer." (PMID 35230214, 2022). "In our data, the overlaps of Drp1 and RPL22 expression was observed in the cytoplasm of gastric cancer tumors." (PMID 35230214, 2022). "It is the lack of a more putative evidence to confirm the nuclear import of RPL22 and its function in Drp1-inactivated gastric cancer cells." (PMID 35230214, 2022). "Based on the overlaps of Drp1 and RPL22 in the cytoplasm, we speculated that the homologs of RPL22 in the mitochondria might participate in Drp1-mediated dysfunction of mitochondrial dynamics and cell proliferation in gastric cancer." (PMID 35230214, 2022). "In MSI-positive GCs, ACVR2A, RPL22, LMAN1, and STAU2 were observed to have recurrent single base thymine deletions in poly(T) regions and this was confirmed in a screen of an additional 94 gastric cancer/normal paired samples (9 MSI-positive)." (PMID 23237666, 2012).
glioblastoma (6 papers, 2017 to 2024). The most malignant astrocytic tumor (WHO grade IV). "RPL22L1, a component of the 60S subunit regulated by RPL22, has been found to be significantly upregulated in glioblastoma (GBM) and hepatocellular carcinoma (HCC), leading to a poorer outcome for patients." (PMID 39207452, 2024).
lymphoma (6 papers, 2018 to 2025). A malignant (clonal) proliferation of B- lymphocytes or T- lymphocytes which involves the lymph nodes, bone marrow and/or extranodal sites. "In support of this notion, RPL11 (uL5) and RPL22 (eL22) inactivation shortens the latency of lymphoma development in mouse models and is associated with c-MYC upregulation." (PMID 30862070, 2019). "In lymphoma infected with Epstein–Barr virus (EBV), eL22/RPL22 dissociates from the 60S ribosomal subunit and associates with the non-coding viral RNA EBER-1." (PMID 39766272, 2024). "RpL22 plays a vital role in T-cell development and lymphoma formation, the main targets of GaHV-2 transformation." (PMID 32967954, 2020). "Ribosomal protein (RPL22) plays a critical role in regulating lymphoma development." (PMID 34497631, 2021).
breast carcinoma (5 papers, 2019 to 2023). "We further performed a ribosome immunoprecipitation assay using Flag antibody to detect ARHGAP5 mRNA ribosome occupancy mediated by its m6A modification in breast cancer cells transfected with Flag-tagged RPL22 (ribosomal protein L22) upon YTHDF1 silencing." (PMID 36077054, 2022).
endometrial cancer (5 papers, 2017 to 2021). Primary or metastatic malignant neoplasm involving the endometrium (mucous membrane that lines the endometrial cavity). "RPL22 is also mutated in microsatellite-unstable colorectal, and endometrial cancers, at 77%, and 50% frequency, respectively." (PMID 32432546, 2020).
leukemia (3 papers, 2019 to 2025). A malignant (clonal) hematologic disorder, involving hematopoietic stem cells and characterized by the presence of primitive or atypical myeloid or lymphoid cells in the bone marrow and the blood. "Lin28b promotes a substantial increase in lipid content, upon which the survival of Rpl22-deficient leukemias depends." (PMID 41389200, 2025). "Instead, we identified induction of the stemness factor Lin28b in the resulting leukemias, which is a key driver of the enhanced lipid synthesis (TG) that supports Rpl22-deficient leukemia survival." (PMID 41389200, 2025). "Genes upregulated in Rpl22−/− leukemias include many that have previously been implicated in AML pathogenesis." (PMID 41389200, 2025). "Specifically, Rpl22 loss decreases oxygen consumption and increases the dependence of HSCs and leukemias on FAO." (PMID 41389200, 2025). "This is perhaps not surprising because Lin28b is primarily expressed in fetal progenitors, but it does raise the possibility that the progenitor population for the resulting Rpl22-deficient MLL-AF9 transgenic leukemias may be of fetal origin." (PMID 41389200, 2025). "Furthermore, Rpl22-deficient MLL-AF9 knockin mice developed and succumbed to leukemia much more rapidly than their Rpl22+/+ counterparts." (PMID 41389200, 2025). "While our study clearly implicates perturbation of lipid metabolism as the mechanism by which Rpl22 deficiency alters HSC function and promotes leukemia survival, these data are largely derived from in vitro assessments." (PMID 41389200, 2025). "Along with the expression signature, Nile red staining revealed that Rpl22−/− leukemias displayed greater lipid content." (PMID 41389200, 2025). "Altogether, these findings reveal that Rpl22 insufficiency enhances the leukemia potential of HSCs through regulation of FAO and promotes leukemogenesis through Lin28b promotion of lipid synthesis." (PMID 41389200, 2025). "Exome sequencing and other approaches have further shown that mutations in RPL5 (uL18), RPL10 (uL16), RPL11 (uL5), RPL22 (eL22), RPS15 (uS19) and RPS20 (uS10) are present in a variety of cancers, especially leukaemia." (PMID 37526268, 2023). "While we did not observe induced mRNA encoding SREBP-1 in Rpl22−/− leukemias, this is not surprising since their regulation by Lin28b is post-transcriptional." (PMID 41389200, 2025). "The Rpl22−/− leukemia did not exhibit the reduction in oxygen consumption observed in primary Rpl22-deficient LSK cells, suggesting that this defect is not retained during transformation." (PMID 41389200, 2025). "Indeed, Lin28b knockdown reduced triacylglycerol (TG) synthesis preferentially in Rpl22−/− leukemias." (PMID 41389200, 2025). "To gain insight into the molecular basis for the control of lipid metabolism by Rpl22 and to make a broader assessment of the regulation of leukemogenesis by Rpl22, we performed RNA sequencing (RNA-seq) on Rpl22+/+ and Rpl22−/− leukemias that developed in the MLL-AF9 transgenic mice." (PMID 41389200, 2025). "Since increased FAO was required for the enhanced self-renewal exhibited by Rpl22−/− HSCs, we next asked whether enhanced FAO also contributed to increased leukemic potential of the Rpl22-deficient MLL-AF9 leukemia cells." (PMID 41389200, 2025). "However, SCAP and SCD2, both targets of SREBP-1 and critical regulators of TG synthesis, were induced in Rpl22−/− leukemias, suggesting that SREBP-1 activation is also responsible for the augmented production of TG in Rpl22-deficient leukemias." (PMID 41389200, 2025). "The increase in FAO appears to play an important role in maintaining the leukemic potential of Rpl22−/− leukemia cells, since treatment with the FAO inhibitor etomoxir was far more effective in inhibiting colony formation by Rpl22−/− leukemia cells than by their Rpl22+/+ counterparts." (PMID 41389200, 2025).
leukemia (continued). "Irrespective of the gestational origin of the leukemia-initiating cell, Rpl22 deficiency cooperates with MLL-AF9 to lead to both Lin28b induction and the disabling of the recently reported tumor-suppressive activity of Lin28b in postnatal MLL-based leukemogenesis." (PMID 41389200, 2025). "The RNA-seq data generated from Rpl22+/+ and Rpl22−/− CD11b+Gr1+ MLL-AF9 leukemias have been deposited in the GEO database (GSE302046)." (PMID 41389200, 2025). "Mice null for Rpl22 display characteristics of an MDS-like syndrome and develop leukemia at an accelerated rate." (PMID 41389200, 2025). "The link between reduced RPL22 expression and poor survival is also observed in a mouse leukemia model lacking Rpl22." (PMID 41389200, 2025).
prostate carcinoma (3 papers, 2019 to 2025). A carcinoma that arises from epithelial cells of the prostate gland. "The top 10 genes upregulated in TRAMP mice are TNFSF, RPL22, EIF4, SLC2A, LMO2/3, KRT, RPS21, RPS19, RPL21, and NEK of which all 10 were upregulated in human prostate cancer dataset." (PMID 30972102, 2019).
T-cell lymphoma (3 papers, 2018 to 2022). "Ribosomal Protein L22 (RPL22) controls the dissemination of T-cell lymphoma: single copy loss of RPL22 promoted lymphomagenesis and dissemination, while loss of both copies results in mediastinal retention." (PMID 33435549, 2021). "It has been reported that RPL22 controlled the dissemination of T-cell lymphoma." (PMID 35903675, 2022). "Finally, eL22/Rpl22 haploinsufficiency in mouse promotes the development and the dissemination of T-cell Lymphoma by inducing expression of the reprogramming factor Lin28B79." (PMID 29674660, 2018).
acute myelogenous leukemia (2 papers, 2023 to 2025). "We report here that expression of the ribosomal protein RPL22 is frequently reduced in human myelodysplastic syndrome (MDS) and acute myelogenous leukemia (AML), and reduced RPL22 expression is associated with worse outcomes." (PMID 41389200, 2025).
Burkitt lymphoma (2 papers, 2017 to 2022). A rare form of malignant mature B-cell non-Hodgkin lymphoma. "For instance, RPL22/eL22 can bind to Epstein-Barr virus (EBV) small RNA EBER1, and this binding is responsible for EBER1 growth-promoting capability in Akata Burkitt lymphoma cells." (PMID 29207594, 2017). "Furthermore, the interaction between EBER1 and RPL22 was shown to be essential for proliferation and tumorigenicity of EBV-infected Burkitt’s lymphoma cells." (PMID 36423146, 2022).
colon cancer (2 papers, 2017 to 2019). "Interestingly, ectopic expression of RPL22 in HCT116 human colon cancer cells, which express higher levels of RPL22L1 than normal colon epithelial cells, repressed RPL22L1 expression." (PMID 31581233, 2019).
lung carcinoma (2 papers, 2017 to 2022). "The binding of RPL22 to casein kinase 2α inhibits substrate phosphorylation of casein kinase 2α, resulting in lung cancer cell apoptosis." (PMID 35230214, 2022).
Lupus (2 papers, 2014 to 2025). "Further links of C3-LHF1 to Lupus and particularly lupus nephritis also come with its physical association in plasma to peroxidasin, a protein suggested to be an autoepitope in lupus nephritis, or lupus-linked proteins such as RPL22, and WDR1." (PMID 41145914, 2025). "Autoantibodies to histone H3-like centromeric protein A and 60S ribosomal protein L22 were in common with the diagnostic peptides of lupus, so these autoantibodies may be present early on as biomarkers and remain throughout the disease process." (PMID 24908187, 2014). "While our data found a classical engagement of C3 with C3 and C4, nidogen-1 (NID1), and plasminogen (PLG), C3-LHF1 also engaged with other lupus- and autoimmune-related proteins, such as WDR1, RPL22, and PXDN, supporting its mechanism of interacting with surface binders." (PMID 41145914, 2025).